SPTBN1 (spectrin beta, non-erythrocytic 1)
Diseases named in the same sentence as SPTBN1 in open-access papers (continued):
Sharing a sentence is not in itself a finding about the gene and the disease.
interstitial cystitis (1 paper, 2024). A rare chronic debilitating urogenital disease characterized by urinary frequency, urgency, and pelvic pain. "Seven hub genes (SPTBN1, PSME4, CHAC2, ERLEC1, ASB3, STAT5A, and STAT3) were identified as differentially expressed between interstitial cystitis patients and healthy individuals, representing potential therapeutic targets." (PMID 39399486, 2024).
kidney cancer (1 paper, 2022). Primary or metastatic malignant neoplasm involving the kidney. "Based on the Cancer Cell Line Encyclopedia (CCLE) dataset, we observed that SPTBN1 was highly expressed in kidney cancer, compared to that in most of other solid tumors." (PMID 36527113, 2022).
liver fibrosis (1 paper, 2023). "Furthermore, MEF2C directly activates SPTBN1 and consequently induces liver fibrosis." (PMID 36814339, 2023).
malignant uveal melanoma (1 paper, 2023). "In current report, we explore expression patterns of SPTBN1 in pan-cancer, and visualize its prognostic landscape in human cancers, especially in kidney renal carcinoma (KIRC) and malignant uveal melanoma (UVM)." (PMID 37013511, 2023).
microcephaly (1 paper, 2015). A congenital or acquired developmental disorder in which the circumference of the head is smaller than normal for the person's age and sex. "Other genes within the combined network are involved in neuronal progenitor cell proliferation, a common mechanism underlying microcephaly (RAC1 and GNB1) and neuronal development (CEBPB, L1CAM, MAPT, PAK2, SPTBN1, and YWHAE)." (PMID 25781962, 2015).
pancreatic ductal adenocarcinoma (1 paper, 2023). An infiltrating adenocarcinoma that arises from the epithelial cells of the pancreas. "From their prognostic signature, they revealed that SPTBN1 could serve as an independent predictor of predicting OS of pancreatic ductal adenocarcinoma (PDAC) under clinical settings; they also found higher expression of SPTBN1 was associated with longer survival in patients with PDAC." (PMID 37013511, 2023).
renal carcinoma (1 paper, 2023). A carcinoma arising from the epithelium of the renal parenchyma or the renal pelvis. "On the contrary, 3 are linked with a favorable prognosis for renal cancer (SPTAN1, SPTBN1, CAVIN2)." (PMID 37775701, 2023).
serous ovarian cancer (1 paper, 2021). "βII spectrin has been shown to be involved in the resistance of serous ovarian cancer to cisplatin treatment, and the fusion of SPTBN1 with other genes also causes resistance." (PMID 33390831, 2021).
ZIKV infection (1 paper, 2025). "Since AIS and nodes of Ranvier are essential for action potential initiation and propagation, it is conceivable that the simultaneous reduction of Ank3, Sptbn1, and Epb41l3 due to ZIKV infection can alter functions and structures of these excitable axonal domains." (PMID 39848964, 2025).
tumor (30 papers, 2008 to 2025). "We did find significant associations between SPTBN1 expression in tumor immune cells infiltration in KIRC and UVM." (PMID 37013511, 2023). "Of note, mounting evidence revealed differential SPTBN1 expression depending on tumor stage, with reduced SPTBN1 frequently associated with cancer progression in different tumor histotypes." (PMID 38069214, 2023). "The loss of SPTBN1 activates Wnt signalling and promotes the acquisition of the stemness feature in tumour cells, ultimately leading to the progression of malignant tumours." (PMID 35075167, 2022). "Four proteins (FSCN1, SIPA1, SPTBN1 or CD59) closely associated with tumor metastasis interacted with FASN and exhibited decreased expression in response to FASN silencing." (PMID 32699531, 2020). "Mutated Sptbn1 was then identified as a potential tumor-rejection antigen." (PMID 34885172, 2021). "We reveal that reducing the abundance of SPTBN1 through siRNA inhibits ammonia–SPTBN1 adduct formation and restores tumor-suppressive TGF-β signaling." (PMID 40311681, 2025). "Tumor-suppressor genes, including APC, BARD1, HMMR (RHAMM), KLLN, LZTR1, MCPH1 (BRIT1), MLH1, NF1, RB1CC1 (FIP200), SLC22A18, and SPTBN1, have been found to increase the risk of disease and tumor development." (PMID 40941673, 2025). "Exploiting exact roles of SPTBN1 in human cancer progression will contribute to tumor prognosis and treatment." (PMID 37013511, 2023). "The relationships between SPTBN1 expression and survival/tumor immunity in KIRC and UVM were further investigated via R packages and TIMER 2.0 platform." (PMID 37013511, 2023). "Yet it’s worth noting that the tumor suppressing and survival predicting roles of SPTBN1 in many types of human solid adenocarcinoma." (PMID 37013511, 2023). "The expression level of TNFSF9 was also distinctly higher in tumor samples from high SPTBN1-expression UVM group compared to ones with low SPTBN1-expression level (Mann–Whitney U score = 245.0, p = 0.01)." (PMID 37013511, 2023). "As demonstrated in revised_Figure 7 A, IHC staining comparison of SPTBN1 expression status in tumor samples from clinical KIRC patients was performed." (PMID 37013511, 2023). "Knocking down SPTBN1 dramatically accelerated tumor growth, as quantified by tumor size and tumor volume." (PMID 36527113, 2022). "As a novel tumor suppressor, SPTBN1 expression is dysregulated in hepatocellular carcinoma, pancreatic cancer, colorectal cancer, ovarian cancer and lung cancer." (PMID 36527113, 2022). "In the present study, we aimed to investigate the aberrant expression pattern of SPTBN1 in ccRCC and its tumor-suppressive role, as well as its interaction with downstream GPT2 to suppress tumor-required glycolysis." (PMID 36527113, 2022). "To further investigate the tumor-suppressing role of SPTBN1 in ccRCC, firstly we detected the expression of SPTBN1 in multiple databases." (PMID 36527113, 2022). "IHC staining results confirmed that the expression of SPTBN1 was remarkably decreased in tumor tissues." (PMID 36527113, 2022). "Upon further research, we demonstrated that the BAP31/SPTBN1 complex regulates the tumor progression through the TGFβ/Smad pathway under the control of miR‐362." (PMID 33210473, 2021). "Decreased SPTBN1 expression promoted sphere formation, tumor development and aggressive phenotypes in HCC cells." (PMID 33390831, 2021). "In our previous study, we have shown that loss of SPTBN1 in PLC/PRF5 and SNU449 HCC cells increased the abilities of sphere formation, xenograft tumor development and invasion, indicating that SPTBN1 is an essential suppressor of tumorigenesis." (PMID 33754058, 2021). "Previous analysis from TCGA consortium already showed a significant down-regulation of RNA transcript SPTBN1 in healthy and non-tumor matched samples when compared to PDAC tissues." (PMID 33383671, 2020).
tumor (continued). "PJA1 overexpression is detected in HCCs and is sufficient to suppress SMAD3- and SPTBN1-mediated TGF-β tumor suppressor signaling, promoting HCC proliferation." (PMID 33457451, 2020). "By analyzing TCGA data and immunohistochemistry staining of tumor tissue, we found that SPTBN1 and SOCS3 were positively coexpressed in EOC patients." (PMID 32516133, 2020). "In addition, by integrating independent databases of TCGA and CPTAC, we further validated that the expression of SPTBN1 was significantly downregulated in tumor tissues compared with normal tissues in KIRC patients at both mRNA and protein expression levels." (PMID 37013511, 2023). "So far, it is unclear whether SPTBN1 expression has close relationship with tumor infiltration of immune cells." (PMID 37013511, 2023). "On the other hand, in cancer with high aggressiveness manner that could metastasize extensively at early stage, like UVM, high expression level of SPTBN1 could exert its pro-cancer effect via EMT to promote tumor metastasis since early stage." (PMID 37013511, 2023). "By binding to the Smad3/4 complex, SPTBN1 might regulate tumor immunity or cancer progression via the TGF-β/Smad signaling pathway." (PMID 37013511, 2023). "SPTBN1 suppresses tumor progression via Wnt/β-catenin, JAK/STAT3 and TGF-β/SMAD pathways." (PMID 36527113, 2022). "In addition, to determine the influence of SPTBN1 in vivo, we established subcutaneously xenograft tumor models using nude mice." (PMID 36527113, 2022). "Finally, we demonstrated that the BAP31/SPTBN1 complex regulated tumor progression through the Smad 2/3 pathway under the control of miR‐362." (PMID 33210473, 2021). "In summary (graphical abstract), we reveal that SPTBN1 functions as a tumor suppressor to stabilize SOCS1 protein, controlling the cellular level of p65 to suppress the expression of inflammatory cytokines, IL-1α, IL-1β and IL-6, and the expansion of MDSCs and Foxp3+Treg cells." (PMID 33754058, 2021). "In addition, mutated Sptbn1-specific CD8+ T cells were detected in tumors and draining lymph nodes in tumor-bearing mice." (PMID 34885172, 2021). "However, the correlation between function of SPTBN1 and cancer prognosis or tumor immunity remains unclear." (PMID 37013511, 2023). "Our present observations may certainly contribute to the future understanding of the tumor suppressor function of SPTBN1 in cancer immune evasion, and may provide a model for testing therapeutic agents against the NF-κB-mediated inflammatory responses and eventually overcome cancer immune escape." (PMID 33754058, 2021). "Our findings reveal a novel mechanism by which the microbial metabolite ammonia disrupts tumor-suppressive TGF-β signaling via structural and functional modification of SMAD3 adaptor SPTBN1." (PMID 40311681, 2025). "The mouse and human data suggest that SPTBN1 and SMAD3 play critical roles not only in TGF-β signaling but also in mediating the inflammatory and tumor-promoting effects of a dysregulated gut microbiome." (PMID 40311681, 2025). "SPTBN1 is a TGF-β signal-transducing adapter protein which is necessary for Smad3/Smad4 complex formation and functions as a tumor suppressor in many cancers." (PMID 35641855, 2022). "Our recent work indicated that PJA1 promotes the ubiquitination of SPTBN1 and p-SMAD3, resulting in reduced activity of the tumor-suppressing TGF-β/SMAD3/SPTBN1-dependent pathway in HCC cells." (PMID 33457451, 2020). "Dysfunction of the TGF-β–regulated SPTBN1/SMAD3/CTCF complex increases stem cell–like properties in HCC cells and enhances tumorigenesis in tumor-initiating cells in a mouse model." (PMID 33457451, 2020). "In addition, the novel SPTBN1-ALK fusion gene may become a potential target for anti-tumor therapy." (PMID 27496196, 2016). "In addition, RT-qPCR analysis revealed that LOXL2 and SPTBN1 were predominantly expressed in normal cell lines, whereas higher levels of NCKAP1L, RUNX2, and WFS1 were detected in tumor cell lines." (PMID 41164190, 2025).
tumor (continued). "The oncogenic SPTBN1–ALK fusion may drive resistance to therapy by enhancing cytoskeletal signaling and tumor adaptability." (PMID 41164190, 2025). "Moreover, SPTBN1 decreased the migration ability of the EOC cells A2780 and HO8910 and inhibited the growth of EOC cells in vitro and tumor xenografts in vivo." (PMID 32516133, 2020). "FASN may bind to SPTBN1 and CD59 to mediate invasion and migration in tumor cells, and regulate the activation of the TGF-β-induced EMT." (PMID 32699531, 2020). "Our study discerned that miR‐21‐related genes, such as ABCB1, SPRY1, ERGE, PIK3R1, SPTBN1, VIM, and others, which experienced downregulation in tumor sites, exhibited a negative correlation with tumor purity and a positive association with T cell infiltration, notably CD8+ T cells." (PMID 40567015, 2025). "by using TIMER 2.0 online tool and adjusting tumor purity, we found that SPTBN1 expression had negative correlations with the expression levels of TNFSF9 (R =-0.238, p = 2.31E-07), PDCD1 (R =-0.191, p = 3.81E-05) and CTLA4 (R =-0.16, p = 5.67E-04) in KIRC (revised_Figure 6B)." (PMID 37013511, 2023). "As previous publications shown, SPTBN1 could play multifaceted roles in different kinds or stages of cancers via functioning in DNA repair to inhibit tumor progression and in EMT to promote tumor progression." (PMID 37013511, 2023). "The different interaction manners between SPTBN1 expression and infiltration of pro-tumor immune cells in different kinds of cancers could provide novel insights into understanding of the paradoxical role of SPTBN1 in affecting the occurrence, development and metastasis of tumor." (PMID 37013511, 2023). "The top negative DEGs, including ABCB1, SPRY1, EREG, PIK3R1, SPTBN1, VIM, KDR, and others, exhibit a negative correlation with tumor purity while demonstrating a strong positive correlation with T‐cell infiltration, especially CD8+ T cells." (PMID 40567015, 2025). "Our results were consistent with those of the meta-analysis such that GSN, SPTBN1, SFRP1 and MAF were down-regulated in most tumor samples with respect to their matched non-tumor samples whereas COX6C, RAD21, GSPT1, NME1 and PTTG1 were up-regulated." (PMID 19116033, 2008). "SPTBN1, which is an important paralog of SPTBN2, and other nonerythroid spectrins exert either oncogenic or tumor suppressor activities by affecting various cancer-related biological processes, including cell differentiation, DNA damage repair, and epithelial-to-mesenchymal transition." (PMID 35968508, 2022).
cancer (29 papers, 2015 to 2025). A tumor composed of atypical neoplastic, often pleomorphic cells that invade other tissues. "The five EMRGs in our model—LOXL2, RUNX2, NCKAP1L, WFS1, and SPTBN1—have been implicated in diverse cancer-related processes." (PMID 41164190, 2025). "Particularly, βII spectrin (SPTBN1) has been implicated in diseases such as cancer, neurological disorders, and cardiovascular diseases." (PMID 38069214, 2023). "Recently, SPTBN1 is reported to be associated with many types of cancers for its essential roles in regulation of EMT and chronic inflammation in TME." (PMID 37013511, 2023). "Specially, for KIRC and UVM, two different cancer types with different manners of aggressiveness, SPTBN1 upregulation is correlated with a low risk and immune infiltration for KIRC, and a high risk and immune infiltration for UVM." (PMID 37013511, 2023). "SPTBN1 has been associated with several malignancies, and its expression varies according to the stage and type of cancer." (PMID 36905477, 2023). "Intriguingly, one of the molecular mechanisms underlying the protective effect of SPTBN1 against cancer progression depends on its ability to restrain oncogenic factors and prevent their nuclear translocation." (PMID 38069214, 2023). "Overall, the findings from present study indicate that SPTBN1 could affect pan-cancer prognosis and closely associate with immune infiltration in TME." (PMID 37013511, 2023). "The SPTBN1 gene inhibits processes such as epithelial–mesenchymal transition (EMT), proliferation, and metastasis of cancer cells, which are associated with lower survival rates and unfavorable prognosis in BC patients." (PMID 40941673, 2025). "Inflammation Control: SPTBN1-mediated regulation of inflammatory pathways positions it as a dual target for treating metabolic disorders and cancer by reducing systemic and local inflammation." (PMID 40301996, 2025). "Previously, we have identified that endogenous toxins, such as reactive aldehydes produced by a WD, disrupt TGF-β signaling, contributing to inflammation and cancer, and that siRNA-mediated silencing of SPTBN1 blocks these toxic effects." (PMID 40311681, 2025). "This suggests that the upregulation of COL11A1 and the downregulation of CAV1, CXCL12, and SPTBN1 in the cancer microenvironment led to the downregulation of IL-6 and IL-33." (PMID 40898538, 2025). "Previous publications suggested that downregulation of SPTBN1 expression was frequently found in many kinds of cancers." (PMID 37013511, 2023). "We firstly analyzed the prognostic patterns of SPTBN1 in human cancers from TCGA database by using univariate Cox regression analysis." (PMID 37013511, 2023). "On the other hand, the correlation between SPTBN1 expression and anti-cancer targeted treatment response in TCGA-UVM patients was explored using IC50 score." (PMID 37013511, 2023). "Then, we explored the potential correlations between SPTBN1 expression and TIICs/immune modulator markers/response of immunotherapy or anti-cancer targeted treatment in KIRC and UVM." (PMID 37013511, 2023). "All these results together strongly indicate that SPTBN1 expression is widely correlated with immunity in cancers." (PMID 37013511, 2023). "SPTBN1 expression often showed a different effect on survival in pan-cancer; upregulation of SPTBN1 was protective to the survival of KIRC individuals, which was contrary from what was found in UVM patients." (PMID 37013511, 2023). "Recently, more and more studies indicated that dysregulation of SPTBN1 had close links with many kinds of human disease, including congenital organ anomalies and cancers." (PMID 37013511, 2023). "Given the multifaceted prognostic role of SPTBN1 in various types of cancer, we subsequently focused on the role of SPTBN1 in KIRC and UVM." (PMID 37013511, 2023). "Overall, cancer tissue had a lower expression level of SPTBN1 frequently in pan-cancer, compared with those in adjacent nontumor one." (PMID 37013511, 2023).